WTAPP1 (WTAP pseudogene 1)
Gene: Transcribed processed pseudogene on chromosome 11 (102,831,703 to 102,832,102, forward strand). Ensembl gene ENSG00000255282.
Diseases named in the same sentence as WTAPP1 in open-access papers:
WTAPP1 is named in the same sentence as 5 diseases in open-access papers, as found by Europe PMC text mining. Sharing a sentence is not in itself a finding about the gene and the disease. The quoted sentences say what the papers report.
non-small cell lung carcinoma (1 paper, 2020). A group of at least three distinct histological types of lung cancer, including non-small cell squamous cell carcinoma, adenocarcinoma, and large cell carcinoma. "Our study was therefore carried out to investigate the role of WTAPP1 in non-small cell lung cancer (NSCLC)." (PMID 32473628, 2020).
pancreatic ductal adenocarcinoma (1 paper, 2022). An infiltrating adenocarcinoma that arises from the epithelial cells of the pancreas. "WTAPP1 was significantly elevated in pancreatic ductal adenocarcinoma and is associated with a poor patient prognosis, and promotes the proliferation and invasive ability of the cells." (PMID 36139062, 2022). "Mechanistically, increased WTAPP1 mRNA levels in pancreatic ductal adenocarcinoma are caused by m6A modification, which stabilizes WTAPP1 mRNA by recruiting the RNA stabilizer HuR by CCHC-type zinc finger nucleic-acid-binding protein (CNBP)." (PMID 36139062, 2022).
Wilms tumor (1 paper, 2015). An embryonal neoplasm characterized by the presence of epithelial, mesenchymal, and blastema components. "WTAPP1, a pseudogene with unknown function, has been reported to be associated with Wilms’ tumor." (PMID 26247464, 2015).
tumor (2 papers, 2020 to 2023). "Compared to healthy tissues, expression levels of WTAPP1 were significantly higher in tumor tissues (p < 0.05)." (PMID 32473628, 2020). "It was observed that the expression of HAND2-AS1 in tumor tissues was significantly correlated with the expression of WTAPP1." (PMID 32473628, 2020). "According to Youden’s index, patients were divided into high (n = 36) and low (n = 32) WTAPP1 expression (tumor tissue) groups, compared to patients in the low WTAPP1 expression level group, patients in the high WTAPP1 expression group level showed significantly lower overall survival rate." (PMID 32473628, 2020).
cancer (1 paper, 2020). A tumor composed of atypical neoplastic, often pleomorphic cells that invade other tissues. "Long non-coding RNA (lncRNA) Wilms Tumor 1 Associated Protein Pseudogene 1 (WTAPP1) has been reported to be a critical player in the angiogenesis and migration of endothelial progenitor cells, while its involvement in cancer biology remains unknown." (PMID 32473628, 2020). "It has been reported that WTAPP1 can promote angiogenesis and migration of endothelial progenitor cells, while its functionality in cancer biology is unknown." (PMID 32473628, 2020). "WTAPP1 may promote cancer cell invasion and migration in NSCLC by downregulating lncRNA HAND2-AS1." (PMID 32473628, 2020). "In conclusion, WTAPP1 is upregulated in NSCLC and promotes NSCLC by downregulating HAND2-AS1 to promote cancer cell migration and invasion." (PMID 32473628, 2020). "We reported that WTAPP1 was upregulated in NSCLC, and WTAPP1 may serve as an oncogene in NSCLC by promoting cancer cell invasion and migration through the downregulation of HAND2-AS1." (PMID 32473628, 2020).